MMP9 (matrix metallopeptidase 9)
Diseases named in the same sentence as MMP9 in open-access papers (continued):
Sharing a sentence is not in itself a finding about the gene and the disease.
cancer (continued). "Out of 24 MMPs, MMP-9 is the only one that is both undetectable in healthy tissues and highly expressed in inflammation and in several diseases, including cancer." (PMID 37626921, 2023). "The upregulation of p38 MAPK by SNCG leads to increased MMP-9 expression, which enhances cancer cell invasion." (PMID 37248432, 2023). "Regarding core targets, it is important to note that MMP9 contributes to the breakdown of the extracellular matrix in various physiological and pathological contexts, including cancer." (PMID 37180727, 2023). "Albrengues and colleagues demonstrated that NE and MMP9, both present in NETs, cleave laminin, inducing the proliferation of dormant cancer cells." (PMID 38201433, 2023). "During carcinogenesis, MMP-9 increases endothelial cell migration and activates the angiogenic switch in tumors through the release of VEGF from the matrix, suggesting the pro-angiogenic role of MMP-9 in cancer tissues." (PMID 36874130, 2023). "Previous studies have shown that CD147 positively correlates with the expression of MMP-2 and MMP-9 in both cancers, suggesting that patients with elevated concentrations of CD147 have a poorer prognosis." (PMID 36982551, 2023). "Numerous clinical and experimental studies have associated an increase in various MMPs particularly MMP-2 and MMP-9 with cancer development." (PMID 36938194, 2023). "MMP-2 and MMP-9 are gelatinases involved in the invasion and metastasis of cancer cells, and their synthesis and secretion are regulated by pathways such as MAPK and FAK/Src." (PMID 38137922, 2023). "Significant positive correlations were found with DC versus cancer stem cells (p = 0.008) and the expression of MMP9 versus cancer stem cells (p = 0.018)." (PMID 37200633, 2023). "Almost all the cancer cell MMP9 positive cases expressed IL-8 (18/19) on IHC, and the correlation was close to being statistically significant (p = 0.056)." (PMID 37296952, 2023). "Our examination of the correlation between cancer cell MMP9 and macrophage infiltration used previously reported data, and revealed a significant association, particularly with CD204-positive M2-like macrophages." (PMID 37296952, 2023). "Much evidence has been reported about several matrix metalloproteinases (MMPs) of cancer, such as MMP2 and MMP9, driving cancer invasion by degrading extracellular matrices." (PMID 37367670, 2023). "MMPs, especially MMP-2 and MMP-9, have been shown to be involved in cancer cell migration and invasion." (PMID 36969058, 2023). "Our results suggest that close interaction with TAMs infiltrating in cancer stroma or cancer nests induces MMP9 expression in ESCC cells, equipping them with more malignant features." (PMID 37296952, 2023). "By immunofluorescence staining, we found that the relative fluorescence intensity of MMP9 in human cancer was significantly stronger than that in the peritoneal tissues." (PMID 38054829, 2023). "Both MMP2 and MMP9 are capable of regulating migration and invasion and serve as important prognostic factors of many cancers." (PMID 37307404, 2023). "NE and MMP-9, which are key components in NETs, cleave laminin to induce the proliferation of dormant cancer cells in lung by activating integrin α3β1 signaling." (PMID 37936694, 2023). "In cancer, neutrophil‐derived MMP‐9 has been gaining attention for its role in promoting metastasis and angiogenesis." (PMID 38062888, 2023). "Our study demonstrates that MMP9 expression in cancer cells leads to shorter overall and disease-free survival." (PMID 37296952, 2023). "It is known that many signaling pathways, including MAPK pathways, mediate MMP-9 expression and regulate cancer invasiveness." (PMID 36900342, 2023). "Matrix metalloproteinases (MMPs), especially MMP9, are thought to be particularly important for cancer invasion and metastasis, due to their ability to degrade ECM barriers." (PMID 37753805, 2023).
cancer (continued). "MMP-2 and MMP-9 play a key role in cancer progression and metastasis by degrading ECM thus, they are important predictive factors for various cancers." (PMID 38069361, 2023). "When analyzing the biological function of intracellular MMP-9 substrates, two-thirds of candidates were autoantigens in cancer or autoimmune diseases." (PMID 37176151, 2023). "Those MMPs, especially MMP-2 and MMP-9, are driving forces for cancer cell invasion and metastases formation." (PMID 35600975, 2023). "The observed inhibitory effects of EF24 were attributed to the reduction of TPA-induced upregulation of matrix metalloproteinase-9 (MMP-9), as a critical mediator of cancer spread." (PMID 38001739, 2023). "The ability of MMP-9 to degrade the extracellular matrix makes it an important protein for the metastatic progression of cancer." (PMID 38068928, 2023). "Kaplan–Meier analyses revealed that MMP9 expression in cancer nests was significantly correlated with overall (p = 0.036) and disease-free survivals (p = 0.038), whereas in stromal cells it was not significantly correlated with either." (PMID 37296952, 2023). "In recent decades, numerous studies revealed the critical role of MMP-9 in cancer development and progression." (PMID 37569509, 2023). "In the ErbB signaling pathway, EGF and its receptor activate MMP9, a protease involved in the proliferation of tumors, resulting in the invasion of cancer cells." (PMID 37311820, 2023). "According to the clinical findings, excessive MMP-1 or MMP-9 are detected in the cancer tissues or saliva specimens of OC patients who consumed AN." (PMID 36961055, 2023). "We also revealed that cancer cell MMP9 is an independent prognostic factor of disease-free survival through multivariate Cox regression analysis." (PMID 37296952, 2023). "The elevated expression of MMP-9 with various pathological conditions, including cancer, highlights the importance of designing, developing, and evaluating new MMP-9 inhibitors." (PMID 37569509, 2023). "Matrix metalloproteinase-2 (MMP2) and matrix metalloproteinase-9 (MMP9) are matrix metalloproteases involved in cancer progression and invasion, and their expression is considered a marker of cell invasiveness." (PMID 37686467, 2023). "Immunohistochemical examinations of colon tissues showed significantly lower neutrophil counts, more granzyme B-positive but fewer MMP9 (gelatinase B)-positive cancer cells and lower numbers of apoptotic cells in mice receiving AAT therapy." (PMID 37532996, 2023). "DNS treatment upregulated Bcl-2 expression while downregulating Bax, MMP-2, MMP-9, mTOR, and Akt levels in cancer cells." (PMID 38192621, 2023). "Chlorogenic acids have been shown to inhibit MMP-9 activity in cultured hepatoma cells, indicating a possible cancer chemoprevention mechanism." (PMID 36903626, 2023). "The downregulated MMP9 disfavored the degradation of the extracellular matrix, suppressing the migration and invasion of cancer cells." (PMID 37156756, 2023). "Several studies have also shown that MMP-2 and MMP-9 play a key role in the invasion of cancer cells, and their increased expression is directly related to the malignancy and aggressiveness of cancer cells." (PMID 37700002, 2023). "This scaffold was supplemented with special pharmacophoric features that inhibit MMP-9 and halt cancer progression." (PMID 37569509, 2023). "The molecular modeling techniques help to design selective MMP-9 inhibitors targeted to anti-cancer therapy." (PMID 37175113, 2023). "Consequently, protein expression levels of PI3K, AKT, MMP2, and MMP9 that are the proteins implicated in cancer progression in the siRNA-treated group were significantly decreased, stipulating that the cancer-promoting effect of MLLT11 might be related to the PI3K/AKT signaling pathway." (PMID 38075552, 2023). "The correlation between IL-8 positivity and cancer nest MMP9 positivity was close to statistical significance (p = 0.056)." (PMID 37296952, 2023).
cancer (continued). "Various studies have found potential applications in biomedicine, antimicrobial activity, antioxidant activity, cancer therapy (inhibitory effect on MMP-9), antiviral, and others." (PMID 37764188, 2023). "MMP-9-activatable imaging probes have been successfully applied for specific imaging of cancer and targeted anticancer drug delivery systems." (PMID 36978072, 2023). "It is believed that vitamin A is related to the production and activity of MMP-2 and MMP-9 in cancer progression, metastasis, and other human diseases." (PMID 38069361, 2023). "This enables cancer cells to metastasize to other sites and establish secondary tumors and, hence, inhibition of MMP-9 can slow down metastasis." (PMID 37894581, 2023). "MMP-9 is a protein known to play a key role in cancer progression and metastasis, including cancer cell invasion, migration, and angiogenesis." (PMID 36829876, 2023). "From this perspective, we review the published research regarding the potential role of MMP-9 in cancer development, paying special attention to the computational and synthetic approaches utilized for the design and development of MMP-9 inhibitors." (PMID 37569509, 2023). "In LC H1299 cells, inhibition of RUNX2 and its target gene MMP-9 by WW domain-containing oxidoreductase (WWOX) significantly suppressed cancer cell migration and invasion." (PMID 37766868, 2023). "NET‐associated proteins, integrin‐αvβ1, and MMP‐9, synergistically capture and activate latent TGF‐β, which interacts with the TGFβR1 on cancer cells and promotes EMT as well as chemoresistance." (PMID 38062888, 2023). "Expressions of MMP-9 and ICAMP1 are closely linked to the growth, invasion, metastasis, and angiogenesis of cancer cells." (PMID 37455847, 2023). "iNOS-derived NO secreted by cancer cells modulates MMP-9 production, thus contributing to neo-angiogenesis, invasion, and metastasis." (PMID 36837539, 2023). "We also measured the activity of MMP-9, another factor important to cancer progression and angiogenesis." (PMID 37686623, 2023). "On the other hand, MMP-9 expression reduction can inhibit the aggressive malignancy of cancer cells." (PMID 37700002, 2023). "This is the first study on ESCC to report that cancer cell MMP9 is an independent prognostic factor in patient survival." (PMID 37296952, 2023). "Some studies have suggested that the Par3–Stat3 and Par3–DDR1 signaling pathways regulate cell–cell junction integrity and the invasion ability of cancer cells via MMP-9 and membrane type 1-MMP, respectively." (PMID 37095487, 2023). "Multivariate Cox regression analyses showed that not only the depth of invasion (p = 0.010) but also cancer nest MMP9 expression (p = 0.026) was an independent indicator of patient poor disease-free survival." (PMID 37296952, 2023). "MMP-9 has been shown to contribute to the pathogenesis of cancer by destroying type IV collagen, elastin, and fibronectin as well as by regulating angiogenesis." (PMID 36938194, 2023). "For example, gelatinases MMP-2 and MMP-9 are highly expressed in human cancer cells, and E-cadherin is mainly expressed in epithelial tissues and has a low expression level in cancer cells." (PMID 36812247, 2023). "Cancer-promoting genes including MMP9, S100A8, S100A9, PORK2, and TGF-β1 were identified as high-expression DEGs in NE-1." (PMID 37333017, 2023). "In contrast, we found that MMP9 was only expressed in the cytoplasm of cancer cells but was expressed at low levels in immune cells." (PMID 37313408, 2023). "This is attributed to the fact that Lcn-2 is also able to promote epithelial-to-mesenchymal transition (EMT) and bind to matrix metalloprotease 9 (MMP9), thereby modulating the metastatic phenotype of cancer cells." (PMID 37958332, 2023). "MMP-9 is an important proteolytic enzyme of MMPs, which is closely related to the invasion and metastasis of a variety of malignant tumors." (PMID 36690987, 2023).
cancer (continued). "Apart from these characteristics, protein isolates of lupin cultivars reduced metastasis of cancer cells by inhibiting the activity of MMP-9 enzyme." (PMID 37947635, 2023). "Many MMP members such as MMP-1, MMP-2, and MMP-9 are overexpressed in cancer and contribute to cancer cell growth, apoptosis, angiogenesis, invasion and metastasis." (PMID 37055381, 2023). "Melatonin inhibits the progression of cancer cells by downregulating MMP-9 and fibroblast growth factor 19 to inhibit the invasion and migration of cancer cells." (PMID 38188676, 2023). "While MMP9 is undetectable in healthy tissues, its expression is significantly up-regulated in inflammation or cancer." (PMID 37507767, 2023). "TNF-α promotes cancer cell invasion via MMP9 production, which can remodel the extracellular matrix during metastasis." (PMID 37041137, 2023). "The activation of the PI3K-AKT-GSK3β pathway downstream of ROR1 is known to promote EMT by increased expression of mesenchymal markers Snail, Twist1, and MMP9, which all play a significant role in the migration and invasion of cancer." (PMID 38213538, 2023). "Multiple reports have shown persistent high expression of MMP-9 in various cancer types and its correlation with metastatic processes." (PMID 37600570, 2023). "MMPs, especially MMP-2 and MMP-9, are usually over-expressed in a wide range of human cancer types, including OS, providing a potential therapeutic target." (PMID 37686148, 2023). "The crucial involvement of MMP-9 in extracellular matrix (ECM) remodeling underscores its significant correlation with each stage of cancer pathogenesis and progression." (PMID 37569509, 2023). "Several MMP-9 inhibitors were enrolled in the clinical investigation against different types of cancer." (PMID 37569509, 2023). "Conversely, MMP9 expression in cancer cells and stroma both indicated better patient survival in uterine cervical carcinoma." (PMID 37296952, 2023). "MMP-9 is a key oncogene affecting cancer cell invasion, and high levels of MMP-9 correlate with an unfavourable cancer prognosis." (PMID 37628949, 2023). "According to the ClinicalTrials.gov database, only a few studies are currently being conducted to determine the predictive value of MMP-9 level on cancer treatment response." (PMID 36765669, 2023). "It has been widely proposed that Bcl‐2 expression in cancer patient samples can promote cell migration, invasion, and metastasis by inducing MMP9 protein expression in various tumors." (PMID 35702822, 2023). "The current study also investigated the effect of adipocytokines towards influencing the expression of the key prognostic marker proteins for cancer progression, β-catenin and MMP-9." (PMID 38068928, 2023). "Dysregulation of MMP9 contributes to progression of many diseases, including cardiovascular diseases, neurodegenerative diseases and cancer, by promoting vascular remodeling and cell invasion." (PMID 37443052, 2023). "The significant link between increased angiostatin and the upregulation of MMP-2 and MMP-9, suggests possible involvement in cancer initiation, progression, and invasion." (PMID 37798646, 2023). "Elevated MMP-9 is known to facilitate cancer cell invasion and metastasis as well as potentiate the invasiveness of OSCC." (PMID 37173998, 2023). "The expression of MMP9 in cancer nests was detected at the invasive front and divided into negative (50 out of 69 cases) and positive (19 out of 69 cases)." (PMID 37296952, 2023). "Using this platform, they found the specific combinations of biomarkers for cancer diagnosis (MMP-9, ADAM-10, and ADAM-17) with joint entropy and programming." (PMID 36831937, 2023). "MMP-9 is abundantly expressed in malignant tumors and contributes to cancer invasion and metastasis." (PMID 37298797, 2023). "Considering downstream regulation, WWOX inhibited the expression of RUNX2 and its target gene MMP9, reducing cancer invasiveness." (PMID 36979157, 2023).
cancer (continued). "By enhancing NF‐κB/p65 pathway in macrophages, SIX1 enhanced the expression of matrix metalloproteinase 9 (MMP-9) and further promoted the invasion of cancer cells." (PMID 36750914, 2023). "Among this family, gelatinases MMP-2 and MMP-9 can promote cancer metastasis by degrading collagen IV and gelatin, alone or in cooperation with other MMPs." (PMID 36765917, 2023). "The low ability of ABCC6-silenced cells to invade the Matrigel was most likely due to the reduced expression and secretion of active forms of the two metalloproteinases MMP2 and MMP9, whose activities have been correlated with the invasive stage of carcinomas." (PMID 38003580, 2023). "A liposome that reverts its charge from negative to positive in the presence of matrix metalloproteinase 9 (MMP9, upregulated in several cancer types) has been recently described." (PMID 35626078, 2022). "MMP-9 is a major member of the zinc metalloproteinase family because it stimulates cancer metastasis by degrading ECM23 and collagens, facilitating cancer cell invasion and metastasis." (PMID 35840633, 2022). "MMPs are among the most-studied proteases, and production of MMPs such as MMP-9 in cancers promotes metastasis and angiogenesis." (PMID 35385679, 2022). "The P5 peptide carried the anticancer drug doxorubicine (Doxo) attached via a linker sequence (PLGSYL) which can be cleaved by MMP-9 enzyme over-expressed in cancer cells." (PMID 35893800, 2022). "EGCG is also effective in the inhibition of MMP-2 and MMP-9, which are responsible for degrading the basement membrane and assisting cell invasion and are commonly overexpressed in cancer." (PMID 35956766, 2022). "Various evidence indicate that MMP-2 along with MMP-9 are overexpressed in malignant tumors, including BC." (PMID 35295962, 2022). "There is a close relationship between increased MMP9 secretion and damage to tissue structures during cancer development." (PMID 35406619, 2022). "Overproduction of inflammatory cytokines, fibrotic proteins such as MMP-2 and MMP-9 expressions, and excess extracellular matrix deposition result in fibrosis, which aids in cancer progression." (PMID 36143462, 2022). "By regulating EMT-related factors (like MMP2, MMP9 and fibronectin) and cell cycle suppressor (p21 and p27), Akt1/p-Akt1 involved in regulating cell motility and growth in various cancer cells." (PMID 35953860, 2022). "MMP9 is produced mainly by monocytes and inflammatory macrophages, as well as by neutrophilic granulocytes and most cancer cells." (PMID 35406619, 2022). "MMP-9 also down-regulates the IL receptor on the surface of T cells, further inhibiting immunity and promoting cancer tolerance." (PMID 36776395, 2022). "Among MMPs, MMP-1, MMP-2, and MMP-9 are reported to be most commonly related to malignant tumors, their metastases, and local invasion." (PMID 36551933, 2022). "In the current work, we found an increment of MMP-2 and MMP-9 levels and their potential enzymatic activity in samples from cancer patients." (PMID 36213817, 2022). "Cancer-associated proteins, such as MYC, IGF-1, and MMP9 were identified as the main hubs in the resulting networks, and it had been previously reported that they were related to tumorigenesis and metastasis." (PMID 35711939, 2022). "Chymase-activated MMP-9 has been shown to be involved in the development and progression of cardiovascular and inflammatory diseases and cancer in patients and experimental models." (PMID 36289761, 2022). "The levels of EMMPRIN and MMP-9 have been identified as markers of cancer and inflammatory diseases, being critical to regulate inflammation and bone metabolism." (PMID 35830122, 2022). "There were three variants remarkably related to cancer risk, including MMP-2 rs243865, MMP-7 rs11568818, and MMP-9 rs3918242." (PMID 35574300, 2022).